ENSG00000145063 (novel transcript)
Synonyms: FLJ33534
Gene: Long non-coding RNA gene on chromosome 2 (11,105,317 to 11,132,821, reverse strand). Ensembl gene ENSG00000145063.
Diseases named in the same sentence as ENSG00000145063 in open-access papers:
ENSG00000145063 is named in the same sentence as 1 disease in open-access papers, as found by Europe PMC text mining. Sharing a sentence is not in itself a finding about the gene and the disease.
ENSG00000145063 shares sentences with these, for which no sentence is quoted: Obesity (1 paper).